ING5 (inhibitor of growth family member 5)
Diseases named in the same sentence as ING5 in open-access papers (continued):
Sharing a sentence is not in itself a finding about the gene and the disease.
lymph node metastasis (2 papers, 2015 to 2016). "Cytoplasmic ING5 expression was positively associated with lymph node metastasis, and negatively with age, lymphatic invasion or CPP32 expression." (PMID 27409347, 2016). "The positive correlation between cytoplasmic ING5 and lymph node metastasis suggested that it could be regarded as a marker for aggressiveness, supported by lower CPP32 (a apoptotic marker) in the cases with cytoplasmic ING5 positive." (PMID 27409347, 2016).
neuroblastoma (2 papers, 2020 to 2022). Neuroblastoma (NB) is the most common solid, extracranial childhood tumor. "In neuroblastoma cells, ING5 is a negatively- regulated target gene of miR-376c-3p, and SAHA down-regulates miR-196-b and miR-543 expression to facilitate the translation of ING5 protein." (PMID 36425530, 2022).
non-alcoholic fatty liver disease (2 papers, 2021 to 2023). "Intriguingly, our recent study demonstrated that JFK suppresses hepatic lipid catabolism and exacerbates the development of obesity and non-alcoholic fatty liver disease (NAFLD) by destabilizing ING5." (PMID 34336836, 2021).
triple-negative breast carcinoma (2 papers, 2017 to 2022). An invasive breast carcinoma which is negative for expression of estrogen receptor (ER), progesterone receptor (PR), and human epidermal growth factor receptor 2 (HER2). "In triple-negative breast cancer cells, miR-193 bound to the 3′-UTR of ING5 mRNA to inhibit its expression and miR-193 inhibitor suppressed cell proliferation through ING5/PI3K/Akt pathway." (PMID 36425530, 2022).
anaplastic astrocytoma (1 paper, 2017). "ING5 overexpression in anaplastic astrocytoma indicated a close link between ING5 protein and the tumorigenesis of anaplastic atrocytoma." (PMID 28915612, 2017).
brain cancer (1 paper, 2025). A primary or metastatic malignant neoplasm affecting the brain. "Consistent with affecting EMT, ING5 has also been seen to regulate stem cell differentiation in several in vitro systems including embryonic stem cells, epidermal stem cells, heart stem cells and brain cancer stem (BTIC) cells." (PMID 39787145, 2025).
Cerebral ischemia (1 paper, 2023). Restriction of arterial blood supply to the brain associated with insufficient oxygenation to support the metabolic requirements of the tissue. "Increased expression of inhibitor of growth protein 5 (ING5) was correlated with an increased apoptotic rate in an undifferentiated SH-SY5Y cell model of cerebral ischemia." (PMID 37380886, 2023).
clear cell carcinoma (1 paper, 2017). "ING5 expression was lower in serous and mucinous adenocarcinoma than endometrioid and clear cell carcinoma, indicating that its close link with the histogenesis of the latter two subtypes." (PMID 29262575, 2017).
dermatitis (1 paper, 2025). An inflammatory process affecting the skin. "A 5-fold increase in the incidence of dermatitis was also seen in the ING5 knockouts that became obvious in middle-aged and old individuals." (PMID 39787145, 2025).
diffuse large B-cell lymphoma (1 paper, 2025). "Consistent with ING5 serving a tumor suppressive role, ING5 KO mice developed germinal centre diffuse large B-cell lymphomas at a rate 6-fold higher than control mice at 18 months of age." (PMID 39787145, 2025). "This work also shows that like animals lacking ING1, loss of ING5 results in the development of diffuse large B-cell lymphomas, confirming its status as a type II tumor suppressor." (PMID 39787145, 2025).
hypertrophic cardiomyopathy (1 paper, 2018). A condition in which the myocardium is hypertrophied without an obvious cause. "Our data show that ING5 upregulated acetylated proteins are enriched in hypertrophic cardiomyopathy (P = 0.036), FoxO signaling pathway (P = 0.036), MicroRNAs in cancer (P = 0.050) and Lysosome (P = 0.050)." (PMID 29416718, 2018).
large cell carcinoma (1 paper, 2016). A malignant epithelial neoplasm composed of large, atypical cells. "Nuclear and cytoplasmic ING5 expression became gradually weaker from Sq, Ad, LCC (large cell carcinoma) to SCC (p < 0.05)." (PMID 27409347, 2016).
non-small cell lung carcinoma (1 paper, 2016). A group of at least three distinct histological types of lung cancer, including non-small cell squamous cell carcinoma, adenocarcinoma, and large cell carcinoma. "In summary, down-regulation expression of ING5 protein could be involved in lung carcinogenesis and closely linked to the histogenesis of non-small cell lung cancers." (PMID 27409347, 2016).
tumor (47 papers, 2011 to 2025). "Nuclear ING5 is negatively correlated with tumor size and depth of invasion, while cytoplasmic ING5 is associated with tumor progression." (PMID 36077605, 2022). "ING5 is the last member of the ING candidate tumor suppressor family that has been implicated in multiple cellular functions, including cell cycle regulation, apoptosis and chromatin remodeling." (PMID 31844418, 2019). "It was demonstrated that cells displaying higher content of miR-196a reveled a decreased ING5 (inhibitor of growth protein 5) expression that was associated to a reduced apoptosis, enhanced invasion and growth of this type of tumor." (PMID 27187371, 2016). "This indicates that in these primary cells ING5 is associated with sustained proliferation, which differs from the apparent role of ING5 in tumor cells." (PMID 25860957, 2015). "Recently, inhibitor of growth gene (ING) family consisting of five genes, ING1 to ING5, was identified as a new tumor suppressor gene family that was implicated in the downregulation of cell cycle and chromatin remodeling." (PMID 21052543, 2011). "Recent study finds mutation and downregulation of ING5 mRNA in oral squamous cell carcinoma, suggesting it as a tumor suppressor gene." (PMID 21750715, 2011). "In the ING5-over-expressing and in the ING5-knockdown cell lines, the effects on cell growth and invasion were investigated: It was found that ING5 over-expression was linked to decreased cell proliferation and decreased colony formation as well, highlighting its tumor-suppressive function." (PMID 31390718, 2019). "However, the exact role of ING5 as a candidate tumor suppressor and the underlying mechanisms are largely unknown." (PMID 25938545, 2015). "According to TCGA (LIHC-TCGA), ING5 mRNA expression was positively correlated with tumor status, a high level of serum alpha-fetoprotein (AFP) (>400 ng/ml), vascular invasion, and histologic grade." (PMID 39247819, 2024). "T antigen and ING5 expression sequentially increased from normal liver tissue, para-carcinoma and tumor tissue from Alb/JCPyV T antigen transgenic mice." (PMID 39247819, 2024). "ING5 suppresses proliferation, migration, invasion and tumor growth of various cancer cells via the suppression of EGFR/PI3K/Akt, IL-6/STAT3, Akt/NF-κB/NF-κB/MMP-9 or IL-6/CXCL12 pathway." (PMID 36425530, 2022). "ING5 is the last member of ING protein family as TSGs with inhibitory roles in tumor development and progression." (PMID 36056353, 2022). "The in vivo results proved that miR-196b-5p acted as a promoter of tumor growth via regulating ING5." (PMID 32308564, 2020). "ING5 often functioned as a tumor suppressor gene due to its inhibition of cell growth and promotion of cell apoptosis in various cancers." (PMID 32206065, 2020). "These biomarkers include ADAM17, MMP2, MMP9, and MMP11, survivin and CK19, vimentin, CXCR4, ING5, and Stanniocalcin2; in all of these examples, these molecules are overexpressed in tumoral GC tissues." (PMID 31249523, 2019). "The seven discordant sites occur in seven protein-coding genes, including CD46 (an immune type I receptor) and ING5 (a tumor suppressor)." (PMID 31850058, 2019). "Tumor cell migration was inhibited in A549 cells as shown by means of a wound healing, and a transwell migration assay, when ING5 was over-expressed." (PMID 31390718, 2019). "In this study, mouse xenograft models were also established to further elucidate the effect of ING5 on tumor growth and invasion." (PMID 31390718, 2019). "ING5, which acts as a class II tumor suppressor, was downregulated in many cancers and was able to suppress cell growth and proliferation, induce apoptosis, and negatively modulate drug resistance by regulating multiple signaling pathways." (PMID 30642385, 2019). "In summary, the current data suggest that ING5 functions as a tumor suppressor by diversely regulating protein lysine acetylation and provide new insights into mechanisms of ING5 inhibition of cancer invasiveness." (PMID 29416718, 2018).
tumor (continued). "Our results, for the first time, demonstrate that ING5 functions as a tumor suppressor by differentially and precisely regulating protein acetylation, in an indirect manner." (PMID 29416718, 2018). "ING5 is a novel member of the ING family whose fundamental role in tumor suppression has only recently been investigated." (PMID 28490335, 2017). "ING5 overexpression suppressed tumor growth of U87 cells in nude mice by inhibiting proliferation and inducing apoptosis." (PMID 28915612, 2017). "Through this pathway and other mechanisms, ING5 induces apoptosis, differentiation and autophagy and decreases proliferation, invasion, metastasis and tumor formation by cancer cells." (PMID 28490335, 2017). "ING5 belongs to candidate tumor suppressor, interacts with histone H3K4me3, and promotes the formation of two different HAT complexes to control the histone acetylation." (PMID 28915612, 2017). "We also observed the anti-tumor effects of ING5 in xenograft models of nude mice and clarified the molecular mechanisms." (PMID 28915612, 2017). "In tumor-bearing nude mouse model, ING5 was demonstrated to suppress the tumor growth by inducing apoptosis and autophagy, and decreasing proliferative ability." (PMID 27409347, 2016). "ING5 overexpression suppressed the xenograft tumor growth by inhibiting proliferation and inducing apoptosis." (PMID 27409347, 2016). "In the nu/nu mice, ING5 suppressed the xenograft tumor growth by tumor volume and weight (p < 0.05), inhibited proliferation, induced apoptosis and autophagy according to immunohistochemistry and TUNEL." (PMID 27409347, 2016). "The ING5 gene, which was more highly expressed in 5637 than in H-bc cells, was systematically studied in both cultured cells and tumor xenografts in nude mice." (PMID 25991669, 2015). "We measured ING5 expression in HCC tumor tissue derived from HBV infections by western blot and immunohistochemistry, and found that ING5 expression was decreased in human tumour samples compared to corresponding pericarcinous tissue." (PMID 26497554, 2015). "The injection of either miR-193a-3p agomiR into 5637 tumor xenografts or of the antagomiR into H-bc tumor xenografts indeed led the opposite changes of ING5 protein overexpression in the tumor tissues." (PMID 25991669, 2015). "This is consistent with the observation in epidermal stem cells, in which ING5 is important for cell proliferation, and with the role of ING5 in replication of MCF7 tumor cells." (PMID 25860957, 2015). "We also found ING5 expression was decreased in tumor tissue of HCC patient with HBV infection compared to its expression in para-carcinoma tissues." (PMID 26497554, 2015). "To define the role of ING5 in tumor growth ability in vivo, we established mouse xenograft models with A549 ING5 and A549 control cells by subcutaneous injection." (PMID 25938545, 2015). "ING5 expression was negatively correlated with tumor size, lymph node metastasis, and TNM staging (p < 0.05)." (PMID 25980581, 2015). "Our data show that by interacting with INCA1, ING5 exerts tumor-suppressive function by inhibiting colony formation and cell proliferation, and increasing Fas-antibody-induced apoptosis." (PMID 21750715, 2011). "We found a significant reduction of ING5 expression in AML patients, which supports a function of ING5 as a tumor suppressor." (PMID 21750715, 2011). "Among the nine interacting partners of INCA1, ING5 is a new member of the candidate tumor-suppressor ING family." (PMID 21750715, 2011). "Taking these findings together, ING5 might be used as a target for the anti-tumor effect of SAHA in various cancer cells." (PMID 35747809, 2022).
tumor (continued). "Interestingly, inhibition of the ING5-associated MOZ/MORF acetyltransferases also induces senescence and prevents tumour growth." (PMID 33925563, 2021). "The ectopic expression of miR-200b/200a/429 caused tumor formation in nude mice injected with the nontumorigenic human ovarian epithelial cell line T80 by targeting inhibitor of growth family 5 (ING5)." (PMID 32377191, 2020). "Importantly, the overexpression of ING5 completely blocked the tumor formation of miR-200b/200a/429-overexpressing T80 cells in nude mice." (PMID 32377191, 2020). "Functional analyses revealed that miR-196b-5p could act as a tumor promoter (“oncomiR”) in CRC through targeting ING5." (PMID 32308564, 2020). "And the expression of ING5 in primary tumor was higher than that in distant metastatic tumor." (PMID 33469513, 2020). "Inhibitor of growth 5 (ING5) is a member of the ING candidate tumor suppressor family, participating in the control of multiple cellular functions, such as the modulation of cell growth, apoptosis, differentiation, the cell cycle, DNA damage repair, and chromatin remodeling." (PMID 32206065, 2020). "Tumor volumes were significantly diminished in the case of ING5 over-expression." (PMID 31390718, 2019). "In addition, CDKN1B and ING5 downregulation in HNC was closely related to increased tumor size, lymph node metastasis, advanced tumor stage, and chemoresistance, which eventually contributed to the poor prognosis in HNC patients." (PMID 30642385, 2019). "However, while the important role of ING5 as a potent tumor suppressor in the progression of human cancers has been frequently documented, the molecular mechanism accounting for the loss expression and dysfunction of ING5 in tumorigenesis is largely unknown and deserves further investigation." (PMID 28490335, 2017). "Indeed, restoration of ING5 expression with a miR-24-resistant ING5 overexpression plasmid completely reversed miR-24-induced cellular phenotypes and blocked xenografted tumor growth in vivo." (PMID 28490335, 2017). "Moreover deregulation of ING5 is observed in different tumors, potentially functioning as a tumor suppressor." (PMID 25860957, 2015). "Because the knockdown of ING5 in MCF7 cells promotes tamoxifen sensitivity, ING5 expression may be associated with tumor progression." (PMID 25860957, 2015). "ING5 overexpression significantly inhibited tumor formation and tumor growth." (PMID 25938545, 2015). "Tumor volumes were significantly decreased by ING5 overexpression." (PMID 25938545, 2015). "The conflicting views of ING5 as a tumor suppressor or an oncogene are clearly context specific." (PMID 21750715, 2011). "Data from tissue array showed that ING5 translocation from the nucleus to the cytoplasm might be a critical event for carcinogenesis and tumor progression in human head and neck squamous cell carcinoma." (PMID 21750715, 2011). "Similarly, ING5 manipulates tumor progression via interaction with different molecules." (PMID 36077605, 2022). "Moreover, ING5 knockdown facilitated tumor growth, that was, the anti-tumor effect of miR-196b-5p inhibitor could be diminished by ING5 knockdown in vivo." (PMID 32308564, 2020). "To investigate whether ING5 is involved in miR-200b/200a/429-induced ovarian tumorigenesis, we overexpressed ING5 in miR-200b/200a/429-stably overexpressing T80 cells and then performed cell proliferation, soft agar, and in vivo tumor formation assays." (PMID 32377191, 2020). "In addition, our data showed that the overexpression of ING5 in T80 cells dramatically abrogated the miR-200b/200a/429 overexpression-induced stimulation of cell proliferation, anchorage-independent growth in soft agar, and tumor formation in nude mice." (PMID 32377191, 2020).